MAVS (mitochondrial antiviral signaling protein)
Diseases named in the same sentence as MAVS in open-access papers (continued):
Sharing a sentence is not in itself a finding about the gene and the disease.
viral infection (continued). "We found that TBK1 and IKKε were recruited to MAVS only in TRAF6-expressing cells upon viral infection." (PMID 29125880, 2017). "For example, ablation of RIG-I or MAVS in a number of virus infection models resulted in increased cell survival, indicating a direct role of dsRNA sensing for the induction of cell death." (PMID 27610098, 2016). "As a result, virus infection was shown to relocate FAK from FAs to the mitochondrion where it binds to MAVS to induce IFNβ." (PMID 26760998, 2016). "In report assay, the results showed that the knockdown of MAVS significantly inhibited PC-induced IFNβ and IFNλ1 promoter activities, implying that PC mediated increase of IFNs expression upon virus infection is MAVS-dependent." (PMID 26906558, 2016). "In VSV-infected cells, the amount of MAVS mRNA was increased, showing the normal cellular response to viral infection as anticipated." (PMID 27997564, 2016). "Systems biology analysis of human responses to yellow fever vaccine induced a type I interferon-mediated response comparable to the MAVS-mediated CD4+ T cell response we present, including upregulation of IRF7 and various ISG including MxB, Viperin, and ISG56." (PMID 26849062, 2016). "In response to viral infection, accumulated and aggregated mitochondrial antiviral-signaling proteins (MAVS) on the mitochondrial outer membrane (OMM) activate interferon regulatory factor 3 (IRF3) and NF-κB." (PMID 28074080, 2016). "MAVS signaling is known to play a role in control of number of viral infections, including dengue and hepatitis C, through the induction of type I interferons." (PMID 26849062, 2016). "Endogenous PCBP2 primarily resides in the nucleus but relocalizes to the cytoplasm where it initiates MAVS degradation on viral infection." (PMID 26348439, 2015). "We observed comparable induction of type I and type III IFN by peroxisomal and mitochondrial MAVS upon viral infection and show that both, mitochondrial as well as peroxisomal MAVS are efficiently cleaved and inactivated in HCV-infected cells." (PMID 26588843, 2015). "Accumulating evidence indicates that MAVS becomes active by forming prion-like filaments in response to virus infection." (PMID 26183716, 2015). "Our data thus show that an autoinhibitory mechanism modulates MAVS activity in unstimulated cells and, on viral infection, individual regions of MAVS are released following MAVS filament formation to activate antiviral signalling cascades." (PMID 26183716, 2015). "In this MAVS deficient situation, infection with a PB2Δ-positive virus led to the same levels of IFNβ and ISG mRNAs as observed in WT virus infection." (PMID 26024522, 2015). "RIG-I-like receptors detect viral RNA in infected cells and promote oligomerization of the outer mitochondrial membrane protein MAVS to induce innate immunity to viral infection through type I interferon production." (PMID 26317833, 2015). "Retinoic acid-inducible gene I (RIG-I) is a cytosolic pathogen recognition receptor that contributes to the innate immune response against viral infection via its adaptor protein mitochondrial antiviral signaling (MAVS)." (PMID 25941664, 2015). "Collectively, our data reveal an autoinhibitory mechanism that regulates these active regions in unstimulated MAVS, thus ensuring a prompt responsiveness of MAVS to virus infection." (PMID 26183716, 2015). "In a recent publication the MAVS were shown to reside on the MAM, where they appear in close proximity to peroxisomal and mitochondrial MAVS during viral infection." (PMID 26442263, 2015). "With the aim to characterize the activation of the interferon (IFN) response after viral infection by pex- and mitoMAVS we first determined the subcellular localization of endogenous MAVS on both organelles in the HCV-permissive human hepatoma cell line Huh7." (PMID 26588843, 2015). "During virus infection, PCBP2 can associate with MAVS that acts as a scaffold to enhance AIP4-mediated degradation of MAVS17." (PMID 26348439, 2015).
viral infection (continued). "These experiments place pathologic complement activation downstream of viral infection, MAVS signaling, and TNF-α signaling and indicate that it contributes to the sepsis-like syndrome." (PMID 24743949, 2014). "Based on the nuclear translocation of p65 after viral infection, these bright MAVS puncta were observed in a majority of virus-infected cells." (PMID 24569476, 2014). "The mitochondrial antiviral signaling protein (MAVS/VISA/Cardif/IPS-1) is critical for the innate immune response during viral infection, and its function has been well documented in mediating type I interferon production." (PMID 24651600, 2014). "Virus infection was done to induce MAVS aggregation as MAVS overexpression alone induces very low level of aggregates." (PMID 24643253, 2014). "In this work, we demonstrate that MAVS is also critical for cell apoptosis upon viral infection and highlight the dual function of MAVS in innate immunity and apoptosis." (PMID 24651600, 2014). "Respiratory syncytial virus (RSV) NS1 protein can associate with MAVS during early stage of the viral infection, and this association disrupts the RIG-I and MAVS interaction as well as downstream signaling." (PMID 25514371, 2014). "Upon viral infection, TRIM14 undergoes K63–linked polyubiquitination at Lys-365 and recruits NEMO to the MAVS complex, leading to the activation of downstream signaling." (PMID 25514371, 2014). "Our current study defines a novel apoptotic signaling pathway: upon viral infection, MAVS recruits the MAPK kinase MKK7 onto mitochondria, MKK7 phosphorylates and activates JNK2, and JNK2 then initiates the corresponding cell apoptosis." (PMID 24651600, 2014). "This study highlights the convergence of innate immunity and apoptosis on MAVS during viral infection, further substantiating the notion that the mitochondrial outer membrane is the critical signaling platform for cellular stress responses." (PMID 24651600, 2014). "Peroxisomal MAVS mediated the rapid interferon-independent expression of defense factors to provide the short-term protection upon viral infection." (PMID 25514371, 2014). "Upon viral infection, MAVS recruits MKK7 onto mitochondria, followed by MKK7 induced activation of JNK2, which subsequently initiates apoptosis." (PMID 24651600, 2014). "It was recently reported that MAVS forms large aggregates after viral infection and these species form fiber polymers with amyloid properties, which act as functional aggregates as they are highly potent in activating IRF3." (PMID 24058549, 2013). "IFNλ induction depends on the same triggers and signalling pathways that regulate type I IFN expression, with the RIG-I/MAVS/TBK1/IRF3 axis being particularly relevant in mouse embryonic fibroblasts (MEFs) upon viral infection." (PMID 24278020, 2013). "More importantly, we demonstrated for the first time the feedback inhibition of the RLR/MAVS/IRF3-mediated antiviral innate response by activation of WNT/CTNNB1 pathway induced upon viral infection." (PMID 23785285, 2013). "Recent studies have provided insights into the mechanisms by which RIG-I and MAVS are activated upon viral infection." (PMID 23951545, 2013). "Recent studies have revealed that Mitochondrial Antiviral Signaling (MAVS) protein plays an essential role in the inhibition of viral infection through type I interferon (IFN) pathway." (PMID 23249700, 2012). "In the present study, we demonstrate for the first time that MAVS undergoes extensive tyrosine phosphorylation upon viral infection." (PMID 22844514, 2012). "In contrast, NDV infection significantly down-regulated the level of MAVS mRNA These results suggested that the effect of viral infection on MAVS mRNA down-regulation differs among RNA viruses." (PMID 23028806, 2012). "Viral infection triggers the activation of RIG-I/MDA5 which recruits MAVS by the tandem caspases activation and recruitment domains (CARDs)." (PMID 23249700, 2012).
viral infection (continued). "Following viral infection, the ERGIC reorganizes into small punctate structures allowing TRAF3 to associate with Mitochondrial AntiViral Signaling (MAVS), an essential adaptor of the anti-viral type I IFN response." (PMID 22792062, 2012). "While WT MAVS rescue highly enhanced antiviral response triggered by viral infections, Y9F transfection dramatically impaired these responses." (PMID 22844514, 2012). "Very recently, it has been described that MAVS forms functional prion-like aggregates after viral infection and that these aggregates are required for the activation of IRF3 in the cytoplasm." (PMID 22626058, 2012). "A recent study has shown that viral infection leads to the formation of very large MAVS aggregates, which potently activates MAVS-mediated antiviral signaling." (PMID 23308066, 2012). "In contrast, retention of TRAF3 at the ER-to-Golgi vesicular transport system blunted the ability of TRAF3 to interact with MAVS upon viral infection and consequently decreased type I IFN response." (PMID 22792062, 2012). "Reciprocally, mild overexpression of Sec16A or p115 in Hec1B cells increased the activation of IFNβ, ISG56 and NF-κB -dependent promoters following viral infection and ectopic expression of MAVS and Tank-binding kinase-1 (TBK1)." (PMID 22792062, 2012). "In the present study, we demonstrated for the first time that MAVS undergoes extensive tyrosine phosphorylation following viral infection." (PMID 22844514, 2012). "Specifically, our evidence suggests that MAVS tyrosine phosphorylation triggered by viral infection plays positive regulatory role in the MAVS signaling pathway." (PMID 22844514, 2012). "Recent studies have demonstrated that, in response to viral infection, the MAVS adaptor protein relays innate immune signaling from cytosolic sensors to NFκB and IRF activation that up-regulate antiviral cytokine production." (PMID 22110409, 2011). "Strikingly, the level of the MAVS protein decreased over time, and a 55KD band, likely a cleavage product of MAVS, appeared at a later time point after viral infection." (PMID 21677781, 2011). "In response to viral infection, NFκB activation downstream of MAVS and IKKβ is essential for gene expression and secretion of antiviral cytokines." (PMID 22110409, 2011). "Upon viral infection, mitochondrial antiviral signaling (MAVS) protein serves as a key adaptor to promote cytokine production." (PMID 22110409, 2011). "We surmise that the effects of MAVS deficiency on γHV68 acute infection is likely under-estimated, providing that MAVS is critical for interferon production in response to viral infection." (PMID 20686657, 2010). "During early stages of viral infection, γHV68 activated IKKβ in a MAVS-dependent manner, a signaling event that is likely triggered by a variety of pathogens." (PMID 20686657, 2010). "In fact, previous studies demonstrated that mutations in either of these two ubiquitin binding domains in NEMO leads to an impairment in the activation of type I interferon production by viral infection or overexpressed MAVS." (PMID 20161788, 2010). "Upon viral infection, the mitochondrial antiviral signaling (MAVS)-IKKβ pathway is activated to restrict viral replication." (PMID 20686657, 2010). "The present results suggest a biphasic regulation or “immune-editing”, whereby TRAF3 is Lys63 polyubiquitinated early after virus infection to bridge protein-protein interactions between MAVS and TBK1/IKKε." (PMID 19893624, 2009). "Single stranded RNA (ssRNA) virus infection activates the retinoic acid inducible gene I (RIG-I)- mitochondrial antiviral signaling (MAVS) complex, a complex that coordinates the host innate immune response via the NF-κB and IRF3 pathways." (PMID 19956647, 2009). "This study describes a novel role for MAVS in controlling viral infections through the induction of apoptosis, and identifies viral proteins which inhibit this host response." (PMID 19404494, 2009).
viral infection (continued). "IPS-1/MAVS/VISA/Cardif is an adaptor protein that plays a crucial role in the induction of interferons in response to viral infection." (PMID 18307765, 2008). "The mitochondrial antiviral-signaling protein (MAVS) may be important for the formation of the NLRP3 inflammasome in response to viral infection." (PMID 40298704, 2025). "To explore whether TRIM22 modulates MAVS ubiquitination under viral infection conditions, we employed IAV-infected cells with either overexpression or knockdown of TRIM22." (PMID 40162781, 2025). "CSFV infection triggers the secretion of cytokines and the synthesis of antibodies; this viral infection activates downstream signaling molecules, including MAVS, IRF3, and NF-κB, through the engagement of receptors such as RIG-I, MDA5, and TLR3 (with a primary focus on RIG-I)." (PMID 40001503, 2025). "Notably, this virus-induced phosphorylation was significantly attenuated in ASK1 knockout cells, suggesting that ASK1 is required for robust MAVS phosphorylation during viral infection." (PMID 40837220, 2025). "MAVS is instrumental in the innate immune response to viral infections." (PMID 40944942, 2025). "These IFIH1 (MDA5) mutation alleles can activate Mitochondrial Antiviral Signaling Protein-dependent signaling pathways in the absence of viral infection or without bound viral RNA ligands." (PMID 39840076, 2024). "In addition, we found that both the heterologous expressions of the σ3 protein and the σ3 protein during viral infection were both co-localized with MAVS." (PMID 38757961, 2024). "Interestingly, Cys508 palmitoylation does not regulate MAVS mitochondrial outer membrane localization at resting state; however, it stabilizes MAVS aggregation on the MOM upon virus infection, therefore promoting RLR signaling and innate antiviral immunity." (PMID 39141356, 2024). "We hypothesize that an increase in dsRNA following ADAR-KO53 triggers a similar MAVS-mediated stress response following viral infection." (PMID 39537590, 2024). "However, upon viral infection, MAVS S-palmitoylation stabilizes its aggregation on the mitochondrial outer membrane and thus promotes subsequent propagation of antiviral signaling." (PMID 39141356, 2024). "TRIM26 was physically associated with MAVS independent of viral infection and reduced MAVS expression." (PMID 38965634, 2024). "As orthoflaviviruses manipulate the structure and function of mitochondria, the predominant location of MAVS, we next examined the effects of viral infection on mitochondrial morphology via immunofluorescence staining for the outer membrane protein TOM20 and the viral nonstructural protein NS3." (PMID 39282299, 2024). "Among the most mutated genes in the RSW breed are the genes related to immunity, T-cell receptor variable 20-like, mitochondrial antiviral signaling protein (MAVS), and INPP5D (SHIP1), which may be caused by selection for the resistance to viral diseases." (PMID 39456845, 2024). "TBK1 could recruit to STING or MAVS during viral infection, which localized closely to the endoplasmic reticulum." (PMID 37854611, 2023). "Thus, SAMHD1 suppresses MAVS activation in response to viral infection, impairs IKKε recruitment to MAVS, and inhibits IKKε phosphorylation upon virus infection." (PMID 37328105, 2023). "Furthermore, our study showed that WDR77 is recruited to MAVS upon virus infection and prevents the formation of MAVS prion-like filaments, indicating its critical role in regulating IFN-β induction." (PMID 37563140, 2023). "As expected, acetate lost the capacity to enhance IFN-I production and IRF3 phosphorylation in Mavs−/− BMDM, nor to protect against IAV infection in Mavs−/− mice, demonstrating that MAVS was indeed involved in the mechanism by which acetate protected the mice from viral infection." (PMID 36746963, 2023). "Therefore, mitophagy induced by viral infection leads to decreased MAVS signaling and IFN-I response." (PMID 37692170, 2023).
viral infection (continued). "MAVS acts as a switch in immune signal transduction during viral infection." (PMID 37901251, 2023). "For several virus infections, it was shown that a complex of the viral RNA with RIG-I is stabilized by the association with mitochondrial antiviral-signaling protein (MAVS), and this can mediate activation of STING, resulting in a cGAMP-independent IFN-I response." (PMID 37253946, 2023). "During later viral infection, MAVS activity is negatively regulated by various mechanisms." (PMID 37563140, 2023). "In addition to RLRs, viral infection induces the aggregation of MAVS on the MOM and forms prion-like fibers that are resistant to detergent and proteases." (PMID 36980296, 2023). "Viral infection of cells activates MAVS and may affect its interactions with other cellular proteins." (PMID 37328105, 2023). "Aggregated MAVS acts as a central hub for signal transduction, leading to changes in the expression of several genes involved in inflammation, apoptosis and cell cycle as part of the cellular response against viral infection." (PMID 36876111, 2023). "Furthermore, MAVS filament formation reveals structural and functional variability after viral infection." (PMID 37901251, 2023). "To examine whether endogenous SAMHD1 and MAVS interact in cells during viral infection, we infected monocytic THP-1 cells with Sendai virus (SeV) for 6 h and then performed IP using SAMHD1 antibodies." (PMID 37328105, 2023). "This suggests that CH inhibits viral infection through the MAVS signaling pathway." (PMID 37711616, 2023). "This hypothesis is supported by a previous study showing that a decrease in MMP impaired MAVS-mediated antiviral signaling in the mitochondria, leading to higher viral infection." (PMID 37612597, 2023). "Therefore, CH stimulates an antiviral response in murine macrophages and mice by preventing viral infection through the RIG-1-mediated MAVS pathway." (PMID 37711616, 2023). "In the case of viral infection, attenuated levels of MAVS may result in promoting SARS-CoV-2 viral infection and consequently promoting the viral evasion." (PMID 35970857, 2022). "Furthermore, it was observed that the early activation of STAT2 during viral infection was mainly regulated by the RIG-I/MAVS-dependent pathway." (PMID 36148221, 2022). "In addition, viral infection induces expression of TAX1BP1, which recruits the E3 ligase Itch to add on K48-linked ubiquitination to MAVS for MAVS degradation in terminating MAVS signaling." (PMID 35795661, 2022). "Most of the ubiquitination of MAVS only occurs during viral infection." (PMID 36505476, 2022). "This modification promoted the formation of prion-like aggregates of MAVS after viral infection." (PMID 36620540, 2022). "Several studies have demonstrated that MAVS could be modified by ubiquitination during viral infection." (PMID 35171955, 2022). "In addition, it is also thought that subcellular localization of MAVS determines the signaling activated during viral infection that controls ISG expression." (PMID 36148221, 2022). "Conversely, except for sensing viral infection signaling, MAVS could also sense cellular stress and activate the antioxidant response by activating NF-κB signaling pathway." (PMID 35844503, 2022). "Moreover, the activated caspase-3 can cleave cGAS, mitochondrial antiviral signaling protein (MAVS), and IRF3 to prevent the production of IFN-I during virus infection-caused apoptosis." (PMID 36189363, 2022). "During viral infection, the polyubiquitin translocation of MAVS induced by RNF34 (a cytosolic E3 ubiquitin ligase) could be recognized by NDP52 (ubiquitin receptor), resulting in the degradation of impaired mitochondria by autophagy." (PMID 35844503, 2022). "It seems that at resting states, the levels of MAVS-K63-linked ubiquitination remain low by OTUD3, while upon viral infection, OTUD3 is inactivated by SIRT1-mediated K129 deacetylation, allowing for the buildup of K63-linked ubiquitination of MAVS for its activation." (PMID 35795661, 2022).